IL31RA (interleukin 31 receptor A)
Diseases named in the same sentence as IL31RA in open-access papers (continued):
Sharing a sentence is not in itself a finding about the gene and the disease.
lymphoma (2 papers, 2018 to 2023). A malignant (clonal) proliferation of B- lymphocytes or T- lymphocytes which involves the lymph nodes, bone marrow and/or extranodal sites. "IL-31 was upregulated in mouse lymphoma, whereas its receptor Il31ra was persistently upregulated in Trpv1-expressing sensory neurons in mice with CTCL." (PMID 36520531, 2023).
ovarian carcinoma (2 papers, 2022 to 2024). A malignant neoplasm originating from the surface ovarian epithelium. "Switching to ovarian cancer, the JNK-STAT pathway in tumor invasion and metastasis is activated by IL-31 in the overexpressing, tumoral cells (IL-31RA+), with a possible correlation with different clinical presentation and prognosis." (PMID 35742951, 2022).
prurigo nodularis (2 papers, 2025). Prurigonodularis (PN) is a skin disease in which hard crusty lumps are formed on the skin that itches intensely. "Taken together, these findings suggest that targeting the interleukin-31 receptor A provides broad modulation of prurigo nodularis' underlying pathophysiology, further supporting the central role of interleukin-31 in the disease’s progression." (PMID 40070611, 2025). "Nemolizumab is a monoclonal antibody that targets the interleukin-31 receptor alpha (IL-31RA), which is key in mediating pruritus and inflammation in skin conditions like prurigo nodularis." (PMID 40070611, 2025).
cardiac hypertrophy (1 paper, 2023). "Candidate gene identification analyses of exercise-induced cardiac hypertrophy identified five potential regulatory transcripts: IL31ra, Fam167b, Tafa5, Crip3, and Nanos1 (p < 0.01)." (PMID 37178122, 2023).
cholangiocarcinoma (1 paper, 2023). A carcinoma that arises from the intrahepatic biliary tree (intrahepatic cholangiocarcinoma) or from the junction, or adjacent to the junction, of the right and left hepatic ducts (hilar cholangiocarcinoma). "RiskScore of cholangiocarcinoma patients with 10 genes calculated followed the formula: The RiskScore=0.429*VEGFC -0.434*NFKBIA-0.884*NLRX1+0.54*AKT1+0.629*CSRP1+0.406*EPO+0.833*IL31RA+1.023*LEP+0.341*MUC4+0.363*SEMA4B." (PMID 36817485, 2023).
colon carcinoma (1 paper, 2017). "High expression of IL31RA was also found in 10/15 and 12/15 breast and colon carcinoma specimens, respectively." (PMID 28147314, 2017). "We chose to work with MC38 and CT-26 colon carcinoma cells that highly express both IL31 and IL31RA." (PMID 28147314, 2017).
familial medullary thyroid carcinoma (1 paper, 2015). An instance of thyroid medullary carcinoma that is caused by an inherited modification of the individual's genome. "There are no reports on the relationship between familial medullary thyroid carcinoma (FMTC) associated with cutaneous amyloidosis (CA) and RET or OSMR/IL31RA gene mutations." (PMID 26356818, 2015).
follicular lymphoma (1 paper, 2020). Follicular lymphoma is a form of non-Hodgkin lymphoma characterized by a proliferation of B cells whose nodular structure of follicular architecture is preserved. "The elevation of IL-31/IL31RA signaling was indicated to be responsible for primary follicular lymphoma cell proliferation." (PMID 32528891, 2020). "The expression of IL-31 and IL31RA was found to be higher in lymph nodes from follicular lymphoma patients with grade IIIa compared with grade I/II." (PMID 32528891, 2020).
glioblastoma (1 paper, 2017). The most malignant astrocytic tumor (WHO grade IV). "The mRNA and protein levels of IL31 and IL31RA were evaluated in cell lysates derived from myeloma, leukemia, melanoma, glioblastoma, and several carcinoma cell lines of both mouse and human origins." (PMID 28147314, 2017).
glioma (1 paper, 2021). A benign or malignant brain and spinal cord tumor that arises from glial cells (astrocytes, oligodendrocytes, ependymal cells). "However, the role and mechanism of IL31RA in glioma progression are still unclear." (PMID 33553434, 2021). "Therefore, IL31RA is expected to be a potential therapeutic target in glioma." (PMID 33553434, 2021).
influenza (1 paper, 2023). An acute viral infection of the respiratory tract, occurring in isolated cases, in epidemics, or in pandemics; it is caused by serologically different strains of viruses (influenzaviruses) designated A, B, and C, has a 3-day incubation period, and usually lasts for 3 to 10 days. "After individual siRNA treatment and then FYW exposure, we found that IFN signaling was still reduced upon influenza exposure, only abrogated by 1.2, 1.3, and 1.4-fold in the case of EGR2, IL31RA, and ATP6VD02, respectively." (PMID 38322710, 2023).
mite infestation (1 paper, 2023). Infestations with arthropods of the subclass acari, superorder Acariformes. "Mite infestation and IL-31 administration increased the LLS counts and upregulated DRG neuronal IL-31RA expression, and the LLS counts showed a close correlation with DRG neuronal IL-31RA expression in the NC/Nga and BALB/c mice." (PMID 36674561, 2023).
osteoporosis (1 paper, 2024). A condition of reduced bone mass, with decreased cortical thickness and a decrease in the number and size of the trabeculae of cancellous bone (but normal chemical composition), resulting in increased fracture incidence. "In addition, cluster 2 contained transcripts without prior established association with BMD, osteoporosis or bone cell signaling (e.g., IL31RA, ELTD1, ZNF277)." (PMID 38791593, 2024).
primary cutaneous amyloidosis (1 paper, 2023). Cutaneous amyloidosis refers to a variety of skin diseases characterized histologically by the extracellular accumulation of amyloid deposits in the dermis. "For example, the S489F mutation in IL-31Rα leads to primary cutaneous amyloidosis." (PMID 37116708, 2023).
thymoma (1 paper, 2021). A neoplasm arising from the epithelial cells of the thymus. "The findings about different expression of inflammatory gene such as IL12A and IL31RA in thymoma with or without MG further confirmed the evidence that the incidence of MG may associated to infection." (PMID 34777476, 2021).
cancer (15 papers, 2017 to 2024). A tumor composed of atypical neoplastic, often pleomorphic cells that invade other tissues. "A few reports in the literature have recently implicated the IL-31/IL31RA axis in cancer." (PMID 33553434, 2021). "In recent years, a few literatures implicated the involvement of the IL-31/IL31RA axis in cancer." (PMID 32528891, 2020). "In this study, we found that IL31RA is required for cancer stem cell (CSC)-like properties, invasion and metastasis of BLBC cells, implicating that specific targeting of this protein represents a potential therapy for BLBC treatment." (PMID 32528891, 2020). "Silencing of IL31RA suppresses the cancer stem cell-like properties, migration, and invasion of BLBC cells in vitro as well as tumor growth and metastasis in vivo." (PMID 32528891, 2020). "Intriguingly, both IL31RA-knockdown clones showed the reduced cancer stem cell-like properties that determined by tumorsphere formation assay." (PMID 32528891, 2020). "We show that IL31 and its receptor, IL31RA, are highly expressed in various human and mouse cancer cell lines, as well as in tumor specimens from cancer patients." (PMID 28147314, 2017). "Here, we investigated the expression of IL31 and its receptor (IL31RA) in various cancer cell lines and human tumor specimens." (PMID 28147314, 2017). "Overall these results indicate that certain tumor types highly express IL31 and/or IL31RA, and thus suggest a potential role for the IL31-IL31RA axis in cancer." (PMID 28147314, 2017).
tumor (14 papers, 2014 to 2024). "In contrast, the ‘tumor cells 2’ cluster was characterized by genes associated with protein synthesis (Cmss1, Rpph1, Rps12, Lars2, Ncl2), tumorigenesis (Mt-Rnr2, Hmga2, Mab1b) and cell–cell communication (Gphn, Camk1d, Il31ra, Cmss1, Rpph1), which may be indicative of an inflammatory phenotype." (PMID 39769061, 2024). "IL31RA has been implicated in BC progression and metastasis, while increased expression and activation of CREB are associated with tumor growth." (PMID 37762335, 2023). "After 30 days, vector control MDA-MB-231 developed into xenograft tumors with volume about 800 mm3, IL31RA-knockdown clones had significantly reduced tumor size compared with vector control cells." (PMID 32528891, 2020). "To address this, we isolated CD4+ cells, macrophages, and PMN-MDSCs from the spleen of PyMT tumor-bearing mice and analyzed the expression mRNA levels of IL-31Ra." (PMID 32843492, 2020). "More importantly, the pathological role of IL-31/IL31RA axis in tumor progression is largely unclear." (PMID 32528891, 2020). "We found that IL31 and IL31RA are expressed by several types of tumor cells from both mouse and human origins." (PMID 28147314, 2017). "Tissue microarray analysis of human tumors revealed that a high proportion of tumor specimens express IL31RA in all the tested tumor types." (PMID 28147314, 2017). "We found that IL31 and its receptor IL31RA are differentially expressed by various tumor types from both human and mouse origins." (PMID 28147314, 2017). "Intriguingly, the pathological roles of IL-31/IL31RA signaling in tumor progression remain largely unknown." (PMID 32528891, 2020). "Similarly, tumor cell migration and invasive ability were also robustly stimulated upon IL31RA over-expression." (PMID 32528891, 2020). "Our immunohistochemical results showed that IL31RA was positively expressed in tumour tissues but not in normal brain tissues." (PMID 33553434, 2021). "Additionally, the downregulation of S100B, IL31RA, and CREB5 found here may also promote anti-tumor responses and reduce tumor progression." (PMID 37762335, 2023). "Moreover, we found that IL31RA expression was positive in tumour tissue but negative in normal brain tissue." (PMID 33553434, 2021). "Mutations involving members of the IL-6 receptor gene family like OSMRß and IL-31RA results in dysfunction of the downstream signals like Jak/STAT, Erk1/2, and PI3K/Akt with antiapoptotic effects in several tumor cell lines and this might also be the reason of keratinocyte apoptosis in PLCA." (PMID 25054142, 2014).
infection (8 papers, 2010 to 2023). The state of being infected such as from the introduction of a foreign agent such as serum, vaccine, antigenic substance or organism. "However, subsequent study has shown that IL-31RA knockout mice developed exacerbated type 2 inflammation in the lung following infection with Schistosoma mansoni eggs." (PMID 30647024, 2019).
IL31RA also shares sentences with these, for which no sentence is quoted: systemic sclerosis (2 papers); acute monoblastic leukemia (1); adenovirus infection (1); alopecia (1); Autoimmunity (1); coronary artery aneurysms (1); dermatomyositis (1); diabetes (1); hepatoma (1); Hypertension (1); inflammation (1); leukemia (1); lung carcinoma (1); lupus erythematosus (1); medulloblastoma (1); melanoma (1); myeloma (1); myocarditis (1); neurodevelopmental disorder (1); Obesity (1); Pineal Parenchymal Tumours of Intermediate Differentiation (1); psoriasis (1); restless leg syndrome (1); rheumatoid arthritis (1).